MMP13 (matrix metallopeptidase 13)
Diseases named in the same sentence as MMP13 in open-access papers (continued):
Sharing a sentence is not in itself a finding about the gene and the disease.
rheumatoid arthritis (58 papers, 2006 to 2025). A chronic, systemic autoimmune disorder characterized by inflammation in the synovial membranes and articular surfaces. "Loss of collagen II in rheumatoid arthritis is associated with an increase in matrix-degrading enzymes (e.g., MMP13) and a decrease in collagen II synthesis." (PMID 26785775, 2016). "Both MMP1 and MMP13 are observed in the synovial fluid in pathologic situations such as cartilage breakdown, lymphocyte infiltration, and synovitis in OA, but MMP1 is also associated with rheumatoid arthritis, and MMP13 is the preferred therapeutic target for OA." (PMID 38613068, 2024). "Furthermore, MMP13 is known to be associated with tissue destruction in rheumatoid arthritis." (PMID 34136397, 2021). "It was explained that IL-40 played a role in the upregulation of matrix metalloproteinase (MMP)-13 and chemokine in synovial fibroblasts and also had a function in the regulation of tissue destruction and inflammation in rheumatoid arthritis." (PMID 40870494, 2025). "A notable aspect of this study was the impact of AG on MMPs, including MMP-1, MMP-3, MMP-8, and MMP-13, which are key targets in inflammatory arthritis, including OA and rheumatoid arthritis." (PMID 39125316, 2024). "Previous studies have shown that the genetic knockdown of MAFB in chondrocytes using siRNA (MAFB Si chondrocytes) abrogated the increased matrix metalloproteinase (MMP3 and MMP13) gene expression in rheumatoid arthritis." (PMID 39054551, 2024). "In this study, we employed bioinformatics and machine learning techniques to identify seven key genes associated with rheumatoid arthritis (RA): AKR1B10, MMP13, FABP4, NCF1, SPP1, COL1A1, and RASGRP1." (PMID 39430588, 2024). "Despite treatment with NSAIDS and corticosteroids, similar GCF MMP-13 levels in patients with rheumatoid arthritis and healthy individuals were found which suggests that rheumatoid arthritis tends to overproduce this enzyme." (PMID 37342498, 2023). "In vitro experiments have shown that the JBQG drug serum can inhibit the expression of cytokines (IL-6, IL-8, IL-22, IL-23), chemokine proteins and mRNA expression (MMP-1, MMP-2, MMP-3, MMP-9, MMP-13) in rheumatoid arthritis synovial fibroblasts (RA-FLS)." (PMID 37180723, 2023). "FSTL1 induced MMP3 and MMP13 gene expression in rheumatoid arthritis synoviocytes requiring MAPK, JAK/STAT3 and NF-κB pathways." (PMID 36497076, 2022). "SLC7A5, as an amino acid transporter, participates in cell invasion and regulates the protein levels of MMP3 and MMP13 through mTOR signaling in rheumatoid arthritis fibroblast-like synovial cells." (PMID 35785145, 2022). "The MMP13 and GPSM3 genes play significant roles in rheumatoid arthritis in humans, and the GPSM3 gene has been associated with the risk of developing autoimmune diseases." (PMID 30648118, 2018). "Under inflammatory conditions such as in rheumatoid arthritis and systemic lupus erythematosus, MMP-13 transcription is elevated, and LRP1 shedding is also increased." (PMID 27084377, 2016). "IL-1β increased the transcriptional and translational levels of MMP-1 and MMP-13 in rheumatoid arthritis FLSs, whereas the levels of MMP-2 and MMP-9 were unaffected." (PMID 17697361, 2007). "Gastrodia elata Blume (GE) is a traditional Chinese herbal medicine with anti-inflammatory activity, and according to a study, GE significantly decreased the IL-6, CXCL8, MMP-3 and MMP-13 levels in TNF-induced rheumatoid arthritis fibroblast-like synoviocytes (RA-FLSs)." (PMID 36439173, 2022). "MMP-13 is known to be involved in hemophilic arthropathy and rheumatoid arthritis." (PMID 33213419, 2020). "Under pathological conditions, MMP-13 was expressed in sites where the extracellular matrix is overdegraded, such as OA, rheumatoid arthritis (RA), and various cancers." (PMID 33708990, 2021).
rheumatoid arthritis (continued). "Overexpression of MMP-13 has been observed under numerous pathologic conditions that are characterized by the destruction of collagenous tissue architecture, e.g., in chronic cutaneous ulcers, chronic periodontitis, atherosclerosis, aortic aneurysms and rheumatoid arthritis." (PMID 27084377, 2016). "For example, changes in the levels of some biomarkers like MMP-13 and COMP are also observed in other systemic diseases, such as rheumatoid arthritis, autoimmune disorders, and liver cirrhosis." (PMID 39911590, 2025). "While MMP-13 is expressed during embryonic development to aid bone mineralization, it is overexpressed in pathological conditions such as carcinomas, rheumatoid arthritis (RA), and OA." (PMID 37859901, 2023). "EQ decreased gene expression of MMP-13 and ADAMTS-5 in rheumatoid arthritis and inhibited the NF-κB signaling pathway in mouse macrophages." (PMID 36311191, 2022). "Increased mechanical stress in rheumatoid arthritis results in a rapidly developing inflammation and elevated MMP1 and MMP13 expression, which can induce the degradation of cartilage and subchondral bone matrix." (PMID 30621194, 2019). "In the case of osteoarthritis (OA) and rheumatoid arthritis (RA), members of the collagenase subgroup of the MMPs, specifically MMP-1 and MMP-13, are particularly important in the progression of joint disease." (PMID 19046432, 2008). "Interleukin-21 (IL-21), produced by stimulated CD4+ T immune cells, plays a significant role in the progression of rheumatoid arthritis (RA) via induction of inflammatory factors and matrix metalloproteinases (MMPs) such as MMP-3 and MMP-13." (PMID 32380783, 2020). "Notably, a similar molecular phenomenon has been described in synovial fibroblasts derived from rheumatoid arthritis patients in which MMP-13 upregulation was mediated by TGF-β1 and laminin and not via NFκB upregulation." (PMID 28761774, 2017). "The production of chemokines (such as MCP-1, IL-8) is also increased in endothelial cells, rheumatoid arthritis fibroblast-like synoviocytes (RA-FLS) and mononuclear cells, as is the synthesis of RANK-L by RA-FLS, and that of MMP-1, MMP-3 and MMP-13 in chondrocytes." (PMID 25604317, 2015). "In a rheumatoid arthritis mouse model, the IKKα-dependent non-canonical heterodimer relB-p52 enhances the transcriptional activity of NOTCH and Rbpj, required for the transcription of ADAMTS5 and MMP-13." (PMID 34769441, 2021).
chondrosarcoma (46 papers, 2005 to 2025). A malignant cartilaginous matrix-producing mesenchymal neoplasm arising from the bone and soft tissue. "RANKL production leads to cartilage destruction, as increase in the RANKL/OPG ratio is associated with high MMP-13 synthesis in IL-1β-triggered SW1353 chondrosarcoma cells." (PMID 31546898, 2019). "2- The present study provides evidence of the prognostic significance of MMP-13 in chondrosarcoma of the jaws where the association between this marker and mitotic counts, necrosis and high grade tumors suggests the possible role of MMP-13 in determining the highly aggressive tumors." (PMID 18554405, 2008). "These first results in SW1353 chondrosarcoma cells and isolated chondrocytes displayed the regulation of MMP13 by MIA/CD-RAP and were an important baseline for further investigations." (PMID 36672165, 2023). "Our results showed that NUC1 treatment inhibited the extracellular release of MMPs by blocking TNF-α-induced MMP-1, MMP-3, and MMP-13 expression in chondrosarcoma cells." (PMID 37482815, 2023). "This study demonstrated that NUC1 inhibited the production of NO in LPS-induced macrophages, and reduced MMP-1, MMP-3, and MMP-13 levels in chondrosarcoma cells treated with TNF-α." (PMID 37482815, 2023). "Targeted gene silencing of MIA/CD-RAP with small interfering RNAs led to a significant downregulation of MMP13 expression in the chondrosarcoma cell line SW1353." (PMID 36672165, 2023). "ALE and cynaropicrin both suppress IL-1β-induced NF-κB signaling and inhibit the production of MMP13 in the human chondrosarcoma cell line OUMS-27." (PMID 34444810, 2021). "The steady increase in the expression of ADAMTS16 will cause the inhibition of cell proliferation, migration, and adhesion, and a decrease in the expression of matrix metalloproteinase-13 (MMP13) in chondrosarcoma cells." (PMID 34389038, 2021). "Whilst downregulation of MMP3 and MMP13 has been reported to be indicative of the chondroprotective action of Icariin in SW1353 chondrosarcoma cells stimulated with IL-1β." (PMID 33177241, 2020). "In line with this, we claim a direct effect of Sox9 on the aggressiveness of chondrosarcoma via MMP13." (PMID 33076370, 2020). "The dependent and independent pathways of EIF2α also regulate the invasion and motility of sw-1353 chondrosarcoma cells and the inactivation of Src, Rac1, and MMP13 by Sal." (PMID 30586948, 2018). "The purpose of this study was to investigate immunohistochemicaly the influence of MMP-1, MMP-3, MMP-9 and MMP-13 expression on prognostic parameter in chondrosarcoma." (PMID 29316907, 2018). "Meanwhile, FGF2 has been reported to regulate MMP-13 expression with a time- and dose-dependent relation in chondrosarcoma cells, leading to the degradation of extracellular migration inhibitory factor (MIF) to promote cancer metastasis." (PMID 28740507, 2017). "A previous study showed that MMP-1, MMP-2, MMP-3, MMP-9, and MMP-13 were expressed in high quantities in human chondrosarcoma cells." (PMID 23892595, 2013). "Studies have shown that MMP-1, MMP-2, MMP-3, MMP-9, and MMP-13 exhibit high degrees of expression in human chondrosarcoma cells." (PMID 23892595, 2013). "It was also recently published that A-SAA increased MMP-1, MMP-3 and MMP-13 mRNA and protein expression levels on human chondrosarcoma cells SW1353 and human primary chondrocytes provided from normal articular cartilage." (PMID 23776697, 2013). "Cyr61/CCN1 is also expressed in pancreatic cancer and in human chondrosarcoma cells where it appears to up-regulate MMP13 expression and cell migration." (PMID 23977121, 2013). "TNF-α, another proinflammatory cytokine, induced MMP-12 expression in chondrosarcoma cells when chondrocytes undergo malignant transformation and increased also MMP-13." (PMID 21647363, 2011). "Correlation between MMP-13 expression and clinicopathological parameters of chondrosarcoma patients." (PMID 18554405, 2008).
chondrosarcoma (continued). "In grade III chondrosarcomas, only two cases were examined and revealed strong MMP-13 immunoreactivity." (PMID 18554405, 2008). "The highest collagenase-3 (MMP-13) positive immunoreactivity was found among grade III chondrosarcoma cases." (PMID 18554405, 2008). "The present study was designed to investigate the expression MMP-13 and to correlate its expression with clinicopathological parameters in chondrosarcoma of the jaws." (PMID 18554405, 2008). "We show that the effect of combined treatment on MMP-1 and MMP-13 is observed at the protein level, where the addition of both ligands leads to decreased collagen destruction by IL-1β-activated SW-1353 chondrosarcoma cells over single-ligand treatment." (PMID 19046432, 2008). "The present study was designed to evaluate MMP-13 immunohistochemistry for its presence in a series of chondrosarcoma of the jaws as well as normal cartilage." (PMID 18554405, 2008). "Comparing the intensity of MMP-13 reaction between low and high grade chondrosarcomas revealed that the difference was significant (P < 0.05)." (PMID 18554405, 2008). "We recently described the ability of retinoid X receptor (RXR) ligand LG100268 (LG268) to inhibit interleukin-1-beta (IL-1-β)-driven matrix metalloproteinase-1 (MMP-1) and MMP-13 gene expression in SW-1353 chondrosarcoma cells." (PMID 19046432, 2008). "The immunoreactive pattern of MMP-13 on chondrosarcoma sections showed variable in intensity and percentage of positive cells in different fields in the same case." (PMID 18554405, 2008). "In the current study, it is of interest that, despite the fact that most of analyzed chondrosarcoma cases were positive for MMP-13 expression, there were clear variations in the percentage of positive cells and the intensity of staining." (PMID 18554405, 2008). "The involvement of chondrocytes in MMP-13 production in chondrosarcoma of jaws is related to their roles in matrix turnover." (PMID 18554405, 2008). "Although overexpression of ADAMTS-16 led to decreased MMP-13 expression in chondrosarcoma cells, the role of ADAMTS-16 in OA progression and especially in the meniscal degradation is still unknown." (PMID 40724902, 2025). "Furthermore, COL10A1 and MMP13 are involved in endochondral ossification, a process conserved in matrix-producing chondrosarcoma, and downregulated in dedifferentiated chondrosarcoma." (PMID 38254737, 2024). "The expression of MMP-13 in patients with chondrosarcoma is a matter of controversy." (PMID 38138968, 2023). "Moreover, Rg3 (10, 15 and 20 μM) inhibited MMP-13 expression in IL-1β-SW1353 human chondrosarcoma cells." (PMID 33671187, 2021). "It has been reported that chondrosarcoma produces high amount of MMP-13, suggesting that it may facilitate cartilage destruction through degradation of type II collagene and remodeling of collagenous ECM." (PMID 31139331, 2019). "Here, we showed that AG1478 treatment of HEMC-SS chondrosarcoma cells inhibits the expression of MMP-13 and MMP-3, suggesting that inhibition of EGFR may impair metastatic potential of chondrosarcoma." (PMID 31139331, 2019). "In order to identify compounds which were potentially chondroprotective, ninety six diet-derived bioactives were screened at 10 μM against basal and IL-1-induced MMP13 expression (measured by RT-qPCR) in SW1353 human chondrosarcoma and C28/I2 immortalised human costal chondrocytes." (PMID 30464238, 2018). "Up-regulation of MMP-1 and MMP-13 by IL-1β was previously demonstrated in chondrosarcoma cells." (PMID 24901233, 2014). "Previous studies have shown that HA (800 kDa and higher) suppressed IL-1β-stimulated production of collagenases (MMP-1 and MMP-13) by human articular cartilage explants and isolated chondrocytes, as well as a human chondrosarcoma cell line, through down-regulation of phospho-p38 MAPK." (PMID 23889808, 2013).
chondrosarcoma (continued). "Furthermore, Tan and co-workers very recently found that CTGF stimulation increased the phosphorylation of FAK and ERK via integrin αVβ3 resulting in the migration and expression of matrix metalloproteinase (MMP)-13 in human chondrosarcoma cells." (PMID 19922639, 2009). "While, the weakest reaction for MMP-13 was noted in most cases of grade I chondrosarcoma." (PMID 18554405, 2008). "This factor might be responsible for the currently observed increase expression of MMP-13 among the high-grade cases of chondrosarcoma of jaws." (PMID 18554405, 2008). "The increase in MMP-13 expression may be necessary for the activation of other MMPs that have previously been identified in chondrosarcoma such as MMP-2 and MMP-9 it is also activated by MMP-2, MMP-3, and MTI-MMP." (PMID 18554405, 2008). "MMP-13 is expressed in the majority of chondrosarcoma of the jaws." (PMID 18554405, 2008). "Thus, cleaving type II collagen by MMP13 may favor invasion and motility potential in chondrosarcoma." (PMID 33076370, 2020). "However, MMP13 is also expressed in various diseases involving degradation of collagenous exrtracellular matrix and in malignant tumors, such as squamous cell carcinomas of the head and neck, cutaneous basal-cell carcinomas, chondrosarcomas and melanomas." (PMID 26517808, 2015). "In addition, RIAA inhibited NF-κB-mediated inflammatory markers in various cell models, including nitric oxide in LPS-stimulated RAW 264.7 cells, RANKL-mediated TRAP activity in transformed osteoclasts, and TNF-α/IL-1β-mediated MMP-13 expression in SW1353 human chondrosarcoma cells." (PMID 19712471, 2009). "In chondrosarcoma, IL-1β has been found to regulate p38, which in turn promotes RUNX2-mediated MMP-13 transcription and translation, playing a crucial role in tumor progression." (PMID 40386045, 2025). "IDH mutant chondrosarcoma demonstrated increased expression of collagen 10 alpha 1 (COL10A1) and matrix metalloproteinase 13 (MMP13) in our study." (PMID 38254737, 2024). "In the current study, we suggested a possible regulatory effect on MMP13 mRNA by MIA/CD-RAP via YBX1 in differentiated chondrocytes and SW1353 chondrosarcoma cells." (PMID 36672165, 2023). "To confirm MMP13 regulation by MIA/CD-RAP, we performed an siPOOL-mediated knockdown of MIA/CD-RAP in the human chondrosarcoma cell-line SW1353 and revealed a significant downregulation of MMP13 mRNA after 72 h of siMIA transfection." (PMID 36672165, 2023). "Relative to the levels for IL-1β-treated human chondrosarcoma cell line SW1353, the expressions of MMP-1, MMP-3 and MMP-13 were decreased dose dependently in the 20 μg/mL CZE and 0.4 μg/mL linarin treatment." (PMID 33321982, 2020). "CRISPR/Cas9-mediated knockout of SOX9 in a human chondrosarcoma cell line (HTB94) results in reduced proliferation, clonogenicity and migration, accompanied by an inability to activate MMP13." (PMID 33076370, 2020). "The increases in IL-1β-treated human chondrosarcoma cell line SW1353 were 65.6% for MMP-1, 196.5% for MMP-3 and 119.3% for MMP-13." (PMID 33321982, 2020). "We first verified that transcriptional expression of MMP1, MMP3, MMP13, and ADAMTS4 was upregulated by IL-1β or TNF-α and repressed by I-BET151 in a human chondrosarcoma cell line (SW1353)." (PMID 30786900, 2019). "A chondrosarcoma cell line also expresses MC1R and reduces levels of post‐inflammatory MMP13 transcription in response to αMSH, while healthy primary chondrocytes do not." (PMID 29316344, 2018). "Oncostatin (OSM), a member of IL-6 cytokine family, induces a hypertrophic differentiation, with reduced SOX9 and induced Cbfa1, Coll10, MMP13, VEGF, and RANKL expression in chondrosarcoma cells." (PMID 21647363, 2011). "MMP-3 and MMP-13 gene expression induced by IL-1β, TNF-α and IL-17 was downregulated by mithramycin in human chondrosarcoma SW1353 cells and in primary human and bovine femoral head chondrocytes." (PMID 15987479, 2005).
chondrosarcoma (continued). "As a possible mediator, we could detect matrix metalloproteinase 13 (MMP13), and the influence of MIA/CD-RAP on MMP13 regulation was analyzed in vitro using SW1353 chondrosarcoma cells and primary chondrocytes." (PMID 36672165, 2023). "In SW1353 chondrosarcoma cells, IL-1β (interleukin-1β) induces overexpression of IL-6 (interleukin-6), PGE2 (prostaglandin E2) and Cox-2 (cyclooxygenase 2), which, in turn, activate a series of MMPs, such as MMP-1 and MMP-13." (PMID 31546898, 2019). "Eight of 11 cases (72.8 %) of chondrosarcomas showed a positive reaction for MMP-13, whereas two cases of normal cartilage were negative for this collagenase." (PMID 18554405, 2008). "1- On the basis of positive expression of MMP-13 in the majority of chondrosarcoma of the jaws and absence of detectable expression in normal cartilage, a possible role for this metalloproteinase in the tumoral process is proposed." (PMID 18554405, 2008). "In grade I chondrosarcomas, one of four cases revealed mild staining for MMP-13, while the other three cases showed negative reaction." (PMID 18554405, 2008). "MMP-1 and MMP-3 expression in IL-1β-stimulated chondrosarcoma cells was suppressed by p38 and ERK inhibitors but not by JNK inhibitor, and MMP-13 expression was suppressed by p38 and JNK inhibitors but not ERK inhibitor." (PMID 32213810, 2020). "In consideration of semiquantitative scoring 64% of chondrosarcoma were scored as positive for MMP-1, 46% for MMP-3, 61% for MMP-9 and no for MMP-13." (PMID 29316907, 2018).